GCG (glucagon)
Diseases named in the same sentence as GCG in open-access papers (continued):
Sharing a sentence is not in itself a finding about the gene and the disease.
diabetes (continued). "Although BCAA transamination in rodent liver and amino acid oxidation are usually low, previous work has shown that glucagon induces amino acid catabolism in high doses such as might be relevant to diabetes states in humans." (PMID 37302544, 2023). "DPP4 inhibitors like APL and PVI are potential antidiabetic peptides for lowering glycemic indices, lowering the amount of glucagon, and maintaining insulin levels in type 2 diabetes mellitus, and their activities are indirectly facilitated by the continuous presence of GLP-1 incretin." (PMID 36982902, 2023). "However, it is important to note that elevated glucagon levels can also be seen in other conditions such as cirrhosis and diabetes." (PMID 37623030, 2023). "The use of novel somatostatin receptor 2 antagonists (SSTR2a) may resolve some of the dysfunction in glucagon counterregulation in diabetes, which could help to reduce the burden of treatment-induced hypoglycemia." (PMID 38298268, 2023). "Therefore, increasing the number of insulin-producing beta cells while decreasing the number of glucagon-producing alpha cells turns out to be a promising therapeutic avenue in diabetes treatment." (PMID 37008919, 2023). "Thus, a better understanding of the molecular mechanisms governing glucagon secretion and action and its effect on glycemia has important implications for the pathophysiology of diabetes." (PMID 37140984, 2023). "Butyrate increases insulin sensitivity and reduces glucagon production in the pancreas and stimulates glucose uptake in the muscle and adipose tissue, so butyrate supplementation is important to treatment or prevention of diabetes." (PMID 36014875, 2022). "In addition, since glucagon test is a very simple loading test, we should willingly perform glucagon test when needed for diabetes care in clinical practice." (PMID 35574023, 2022). "Disordered hepatic glucagon response contributes to hyperglycemia in diabetes." (PMID 35046401, 2022). "Therefore, we propose that alterations in the endolysosomal trafficking of glucagon contribute to the hyperglucagonemia of diabetes." (PMID 34923907, 2022). "Moreover, a rationally constructed tri-agonist that mimics the activity of GLP-1, GIP and GCG in one single poly-receptor agonist is able to dramatically improve the outcome of both obesity and diabetes." (PMID 36552107, 2022). "We have shown that maternal RUPP has negative and sex-specific impacts on the regulation of insulin, glucagon and ghrelin in offspring and that, as young adults, male rats may be more prone to develop diabetes." (PMID 36109770, 2022). "Furthermore, we summarize how recent research clearly establishes glucagon as a potential therapeutic target for diabetes." (PMID 35784565, 2022). "Thus, future studies on the regulation of glucagon secretion by targeting ORs expressed on α-cells using odorants will be required for the development of novel treatments for diabetes." (PMID 36104518, 2022). "Use of traditional glucagon kits is low, as reported in previous studies, and the new finding is that the use is low in the totality of countries examined, so that a significant correlation was found between persons with diabetes or type 1 diabetes and units of glucagon sold each year." (PMID 36550552, 2022). "A better understanding of the reasons why glucagon concentrations differ in diabetes (changes in glucagon secretion, its clearance and/or volume of distribution) will help us design informed rational therapeutic approaches to normalize glucose control in these individuals." (PMID 35590248, 2022). "Disordered hepatic glucagon response contributes to hyperglycemia in diabetes via gluconeogenesis." (PMID 35046401, 2022). "SCFAs stimulate glucagon production and signal the hypothalamus as a mechanism of diabetes." (PMID 36936475, 2022).
diabetes (continued). "In addition, biological pathways related to diabetes were identified, including: insulin section, downstream signaling of insulin and glucagon and sensory perception of chemical stimulus." (PMID 35456489, 2022). "The finding of ectopic olfactory signaling events in pancreatic α-cells suggests that OR pathways could be targets for reducing glucagon levels in patients with diabetes." (PMID 36104518, 2022). "Within a population without diabetes, relative lack of glucagon suppression early after a meal was associated with increase of glucose levels over time, suggesting a role of insufficient glucagon suppression in the deterioration of glycemic control." (PMID 36686477, 2022). "However, STZ‐induced diabetes of 20 weeks duration in mice increased mean plasma glucagon from 13 to 78 pM and increased the expression of G6Pase three‐fold." (PMID 35569125, 2022). "Energy metabolism is more active, promoting the occurrence of the glucagon signaling pathway, enabling glucagon to regulate insulin secretion of pancreatic β cells through the cAMP signaling pathway, and reducing the incidence of diabetes." (PMID 35769162, 2022). "We propose that, in addition to enhanced trafficking and secretion through the regulated secretory pathway, the hyperglucagonemia of diabetes may also be due to re-routing of glucagon from the degradative Lamp2A+ lysosome toward the secretory Lamp1+ lysosome." (PMID 34923907, 2022). "Higher serum OCN level is closely related to better blood glucose control, higher insulin sensitivity, increased early-phase insulin secretion of islet β cells and appropriate inhibition of postprandial glucagon secretion of islet ɑ cells in adult patients with type 2 diabetes mellitus." (PMID 36307866, 2022). "Failure to adequately suppress glucagon could lead to the impaired glucose regulation in pre-diabetes and type 2 diabetes." (PMID 36307866, 2022). "The results of this study do not confirm our findings, because carnitine seems to be taken up by muscles and liver, and this process is regulated by insulin and glucagon hormones, while; this study was conducted in subjects with diabetes, whose levels of these hormones are disturbed." (PMID 36704801, 2022). "Notably, miR-320a is significantly downregulated in the human islets of T2D subjects, which is accompanied by an increase in glucagon, and the increased glucagon as a marker of diabetes will worsen hyperglycemia." (PMID 35534828, 2022). "A study suggests that the gene CFTR, which works as a glucose-sensing negative regulator of glucagon secretion in a cell, could lead to glucose intolerance in cystic fibrosis and other kinds of diabetes." (PMID 35642195, 2022). "When insulin and glucagon positive cell numbers were added together, the cell number in the diabetes group was dramatically decreased compared to the control group (p < 0.001), both GQD and metformin groups had higher cell numbers than the diabetes group (P < 0.05)." (PMID 35858880, 2022). "However, while largely underappreciated, glucagon-secreting α cells are also affected in individuals with T1D and contribute to the pathophysiology of diabetes." (PMID 35642629, 2022). "A better understanding of glucagon kinetics and its dysregulation in humans with diabetes that results in abnormalities in circulating plasma glucagon concentrations should lead to rational and informed therapeutic strategies to mitigate both hyperglycemia and hypoglycemia in these individuals." (PMID 35590248, 2022). "There is substantial controversy on the role of glucagon in the pathogenesis of diabetes." (PMID 35872982, 2022). "The compensatory excessive glucagon production may limit the application of GCGR antagonism for diabetes therapy." (PMID 36334626, 2022). "Furthermore, the proportion of CD34-positive cells, which were also positive for glucagon, was significantly increased in alloxan-induced diabetes models." (PMID 36467676, 2022).
diabetes (continued). "Unfortunately, only one of the carriers with glucagon data was free of diabetes at sampling." (PMID 34951657, 2022). "Taken together, although there have been studies evaluating glucagon test and endogenous insulin secretory capacity, to the best of our knowledge, this is the first report to clearly show the relationship between glucagon test and insulin withdrawal in subjects with type 2 diabetes mellitus." (PMID 35574023, 2022). "The hypoglycemic mechanism of liraglutide relies on it can increase insulin secretion and alpha beta-cell action to inhibit glucagon release, which leads to decreased plasma glucose in diabetes patients, and the role of central nervous receptors to increase satiety delayed gastric emptying." (PMID 35392872, 2022). "We hypothesize that a disruption in the trafficking of glucagon and Stmn2 through the endolysosomal pathway might be a possible mechanism by which glucagon secretion becomes dysregulated in diabetes, resulting in glucagon hypersecretion and hyperglucagonemia." (PMID 34923907, 2022). "A further contribution to the G6PD inhibition may be related to the increased glucagon level, which is always present to some extent in diabetes, given that it is known that the injection of glucagon into experimental animals reduces G6PD activity." (PMID 36431166, 2022). "The purpose of this study is to compare serum pancreatic polypeptide (PP), insulin, C‐peptide, and glucagon in different glucose tolerance stages; analyze the influencing factors of PP secretion; and further explore the role of PP in the pathogenesis of diabetes mellitus." (PMID 35437937, 2022). "However, following induction of diabetes, Rab7 maintained colocalization with glucagon, and did appear to colocalize with Stmn2." (PMID 34923907, 2022). "This could also stimulate higher glucagon secretion in patients with diabetes leading to symptomatic hypoglycemia." (PMID 35819935, 2022). "This study may provide a rationale for novel treatment regimens for diabetes by targeting OMP or OR signaling to modulate glucagon secretion." (PMID 36104518, 2022). "Although glucagon and its receptor are ignored in this framework, an increasing number of studies have shown that they play essential roles in the development and progression of diabetes." (PMID 35784565, 2022). "However, a previous study showed that Cys blood levels in diabetes are reduced due to elevated glucagon concentrations, which leads to increased uptake of glutamine and glycine by the liver." (PMID 35859119, 2022). "Importantly, cell Stmn2 content was reduced in islets of diabetic mice, and further reduced after Arg stimulation, thereby showing a different profile from that of glucagon in diabetes." (PMID 34923907, 2022). "A microdevice that offers glucagon supplements in a safe, non‐invasive, and glucose‐responsive manner is ideal for avoiding fatal hypoglycemia consequences from insulin overdosage during daily diabetes treatment." (PMID 35957510, 2022). "Understanding glucagon kinetics is important in diabetes for better management and therapeutics." (PMID 35590248, 2022). "The different action of PAS on the two main regulators of glucose metabolism strengthens the idea that an impaired insulin:glucagon ratio may be the pathophysiological basis of PAS-related diabetes." (PMID 35563608, 2022). "The authors suggested that this gut-derived extrapancreatic glucagon may play an unrecognized role in diabetes secondary to total pancreatectomy." (PMID 36686477, 2022). "The equipment in Polish school nurses’ offices should be supplemented with a working glucometer and blood glucose test strips, and the set of obligatory medications in the school nurse’s office should be supplemented with glucagon for students with type 1 diabetes mellitus." (PMID 36554455, 2022). "We hypothesized that disruption of Stmn2-mediated trafficking of glucagon to the endolysosomes in diabetes contributes to hyperglucagonemia." (PMID 34923907, 2022).
diabetes (continued). "Thus, targeting of the pancreatic α cell and its main secretory product glucagon has potential as a treatment for diabetes." (PMID 35642629, 2022). "In addition, GLUT2 participates in the glucagon and insulin signaling pathways, which are closely related to the occurrence of diabetes." (PMID 35283765, 2022). "The study has shown that, in diabetics, decrease in insulin is not as harmful as an increase in glucagon, as insulin deficient animals that were simultaneously knocked out of the glucagon receptor were normoglycemic." (PMID 35211170, 2022). "The percentage of correct responses in the Diabetes Knowledge Questionnaire was 46.7%, with the lowest scores related to the knowledge of insulin pumps (36.5%), nutritional principles (37.4%), and insulin therapy and glucagon administration (37.9%)." (PMID 36554455, 2022). "Additionally, hypersecretion of somatostatin can disable the counter-regulatory glucagon secretion during insulin-induced hypoglycemia in diabetes." (PMID 33494193, 2021). "The cells co-expressing insulin and glucagon may be pancreatic alpha cells or progenitor cells, which are known to be increased in certain disease conditions including obesity, diabetes, and inflammation as well as in the course of their development." (PMID 33809267, 2021). "The role of glucagon in the pathophysiology of diabetes has long been recognized." (PMID 33758717, 2021). "Considering the role of glucagon in diabetes pathogenesis, it could be considered as a promising pharmacological target either by blocking its effect at the receptor level or by the inhibition of its secretion." (PMID 34502413, 2021). "The mechanism underlying the inappropriate suppression of glucagon secretion that appears after food ingestion in diabetes patients has not yet been identified." (PMID 34199839, 2021). "In 1983, it was shown for the first time that intranasal (IN) glucagon increases blood glucose levels in healthy volunteers, and in 1989–1992 that IN glucagon is similar to IM glucagon in resolving hypoglycemia in normal volunteers and in patients with diabetes, both adults and children." (PMID 34638984, 2021). "So what are the implications of glucagon trafficking through the lysosomal pathway in diabetes?" (PMID 34659118, 2021). "In this review, we focus on aspects of alpha cell biology for possible mechanisms for alpha cell dysfunction in diabetes: proglucagon processing, intrinsic and paracrine control of glucagon secretion, secretory granule dynamics, and alterations in intracellular trafficking." (PMID 34659118, 2021). "Therefore, an exhaustive comprehension of glucagon physiology and its regulatory pathways is critical in designing drugs that improve the effects of hyperglucagonemia in diabetes." (PMID 34502413, 2021). "However, after one century from the discovery of insulin and 98 years from the discovery of glucagon, we should recognize that also this latter hormone plays a critical role in diabetes pathophysiology." (PMID 34572493, 2021). "The ongoing discovery of novel proteins and networks that regulate the secretion of glucagon will shed further light on alpha cell biology in health and disease while also searching for improved means to control hyperglucagonemia and hyperglycemia of diabetes." (PMID 34659118, 2021). "We observed that hepatic Sam68 protein expression is significantly upregulated in diabetic mouse models and in human subjects with diabetes, that glucagon signaling promotes Sam68 translocation from cytoplasm to nucleus, and that Sam68 interacts with CRTC2 both in the nucleus and cytoplasm." (PMID 34099657, 2021). "To test this hypothesis, we use three study groups-pharmaceutical manipulation using metformin, hormonal manipulation using glucagon, and a disease state of diabetes, which is approximated here using the leptin receptor deficient db/db mouse model." (PMID 34357335, 2021).
diabetes (continued). "The phenomenon of unsuppressed glucagon secretion only after oral ingestion appears not only in T2D but also in all types of diabetes including type 1 diabetes, diabetes secondary to chronic pancreatitis or pancreatectomy, and maturity-onset diabetes of the young, among various other types." (PMID 34199839, 2021). "Further investigation into the altered dynamics of glucagon trafficking in the alpha cell in diabetes may reveal key roles for the lysosome in the regulation of glucagon secretion, thus identifying a potential new target for the treatment of hyperglucagonemia." (PMID 34659118, 2021). "The study aims to analyze fasting glucagon in patients with type 2 diabetes and impaired glucose tolerance and correlate it with anthropometric and biochemical parameters in a large proportion of Pakistani people with diabetes." (PMID 33758717, 2021). "Nonetheless, the idea that blocking glucagon action could be an additional therapy for diabetes has sparked interest in the development of potential pharmacological interventions that target the hepatic glucagon receptor." (PMID 34659118, 2021). "Fast-acting glucagon (nasal administration and injected solutions) appears to represent a major breakthrough in the treatment of severe hypoglycemia in insulin-treated patients with diabetes, both adults and children." (PMID 34638984, 2021). "Therefore, uncovering the mechanisms that regulate glucagon secretion from the pancreatic alpha cell is critical for developing improved treatments for diabetes." (PMID 34659118, 2021). "Future studies with a large number of participants and other measurement parameters may further reinforce our current findings and help to understand the pathophysiological role of glucagon in diabetes." (PMID 33758717, 2021). "Furthermore, it is still unclear if specific treatments capable of improving the insulin sensitivity of pancreatic α-cells can also control glucagon levels in patients with diabetes mellitus." (PMID 33020399, 2020). "In conclusion, treatment with canagliflozin in addition to teneligliptin decreases urinary albumin excretion, at least in part, through the reduction of blood pressure and improves a variety of metabolic parameters in a glucagon-independent manner in Japanese subjects with type 2 diabetes mellitus." (PMID 32337293, 2020). "Previous studies reported that Hachimijiogan and Goshajinkigan decreased blood glucose levels in diabetes model animals, and their inhibitory effects on glucagon-induced CREB activation may be attributed to reductions in blood glucose levels." (PMID 32215330, 2020). "Human stem cell-derived SC-β cells develop into islet-like clusters comprised of cells that contain mainly insulin and, to a lesser extent, glucagon and somatostatin, and thus provide a unique opportunity to study diabetes in a human-derived cell culture system resembling native human islets." (PMID 32093375, 2020). "Further complicating glucose homeostasis in diabetes is the direct effect of glucose on the alpha cells; while glucagon secretion is maximally suppressed at plasma glucose concentrations of 5–10 mM, it increases at glucose levels above 10 mM, thus exacerbating hyperglycemia." (PMID 32117057, 2020). "Our findings, which are mainly based on the clonal α-cell line αTC1-6, represent a potentially novel intracellular pathway for the control of glucagon secretion, and may lead to new mechanistic insights in the dysregulation of glucagon secretion in diabetes." (PMID 32117057, 2020). "These questions need to be further explored in order to highlight or confirm the role of glucagon in diabetes development, since GLP1 is broadly used as a drug to stimulate insulin secretion, which in the long run could actually impair beta-cell function." (PMID 33294459, 2020). "Since the incretin hormones and glucagon have some overlapping functions, their combined use could lead to synergistic effects on diabetes and related metabolic diseases." (PMID 32340373, 2020).